RIPK2 (receptor interacting serine/threonine kinase 2)
Diseases named in the same sentence as RIPK2 in open-access papers (continued):
Sharing a sentence is not in itself a finding about the gene and the disease.
brain injury (1 paper, 2023). Acute and chronic (see also brain INJURIES, CHRONIC) injuries to the brain, including the cerebral hemispheres, CEREBELLUM, and brain STEM. "Our findings provide compelling mechanistic evidence that RIPK2 plays a key role in promoting the neuroinflammatory response to ischemic brain injury." (PMID 37777791, 2023).
breast tumors (1 paper, 2025). "Elevated RIPK2 expression in breast tumors correlates with poor prognosis and a higher risk of recurrence, while RIPK2 knockdown inhibits NF-κB signaling, reduces anti-apoptotic proteins, and increases drug sensitivity." (PMID 40406369, 2025).
cholesteatoma (1 paper, 2015). A pathologic process characterized by the proliferation of keratinizing squamous epithelium resulting in the accumulation of keratin and cells in the middle ear and/or mastoid. "Interestingly, the analysis identifies the interaction of RIPK2 with many genes involved in inflammatory and apoptotic processes that are differentially regulated in cholesteatoma." (PMID 25922834, 2015).
COVID-19 (1 paper, 2021). A disease caused by infection with severe acute respiratory syndrome coronavirus 2. "The downregulated genes include ones mediating immune signaling, e.g., RIPK2, RLRP3, and NFKBID, etc., and genes encoding cytokine and chemokines, suggesting impaired immune functions of monocytes from COVID-19 patients." (PMID 35095917, 2021).
diabetic nephropathy (1 paper, 2019). "Hyperglycemia plays a vital role in diabetic nephropathy (DN); autophagy and its potential upregulator receptor-interacting protein kinase 2 (RIPK2) are associated with ROS, which play a potential role in regulating NLRP3, and may be involved in inflammation in DN." (PMID 31485193, 2019). "And renal biopsy for detecting RIPK2, autophagy, and ROS-NLRP3 levels in diabetic patients without renal damage and diabetic nephropathy patients with different classes of renal damage may provide new basis for early diagnosis and new target for advanced treatment in diabetic nephropathy." (PMID 31485193, 2019).
endothelial dysfunction (1 paper, 2025). In vascular diseases, endothelial dysfunction is a systemic pathological state of the endothelium (the inner lining of blood vessels) and can be broadly defined as an imbalance between vasodilating and vasoconstricting substances produced by (or acting on) the endothelium. "There was association with hypertension through inflammation (ERBB4) and oxidative stress and endothelial dysfunction (ERBB4 and RIPK2)." (PMID 40744952, 2025). "Related to hypertension, common off-targets RIPK2 and ERBB4 were predicted to induce oxidative stress and endothelial dysfunction, and the latter also induced inflammation." (PMID 40744952, 2025).
esophageal squamous cell carcinoma (1 paper, 2026). Esophageal squamous cell carcinoma (ESCC) is a type of esophageal carcinoma (EC) that can affect any part of the esophagus, but is usually located in the upper or middle third. "Studies have shown that Serratia marcescens promotes esophageal squamous cell carcinoma xenograft tumor growth through the RIPK2-mediated activation of NF-κB." (PMID 41563982, 2026).
Glucose intolerance (1 paper, 2017). Glucose intolerance (GI) can be defined as dysglycemia that comprises both prediabetes and diabetes. "We found that inhibition of Ripk2 was the defining characteristic of TKIs that attenuated peptidoglycan/muropeptide-induced changes in inflammation and metabolism and that Ripk2 was required for Nod1 ligand-induced lipolysis and glucose intolerance in mice." (PMID 28484277, 2017).
Hypertension (1 paper, 2025). The presence of chronic increased pressure in the systemic arterial system. "In conclusion, this model supports that BTKi-induced AF or hypertension are rather derived from off-target effects partly mediated by TEC and ERBB4 for AF, and RIPK2 and ERRB4 for hypertension." (PMID 40744952, 2025).
invasive carcinoma (1 paper, 2018). A carcinoma that is not confined to the epithelium, and has spread to the surrounding stroma. "In support of IBC cell line data, immunohistochemical (IHC) analysis using a RIPK2 phospho-Y474 antibody, IBC tissue revealed robust and diffuse positive cytoplasmic staining in invasive carcinoma versus non-neoplastic breast tissue (considered a normal control) (p-value < 0.0001)." (PMID 29874851, 2018).
listeriosis (1 paper, 2015). A bacterial infection caused by Listeria monocytogenes. "NOD2-dependent RIPK2 activation is essential for an effective antibacterial response, since RIPK2-deficient macrophages have an impaired pathogen control and RIPK2-deficient mice are highly susceptible to listeriosis." (PMID 26834734, 2015). "In addition to listeriosis, RIPK2 plays essential protective role upon infection with the intracellular bacteria Legionella pneumophila, Chlamydophila pneumonia, and Mycobacterium tuberculosis." (PMID 26834734, 2015). "Activation of RIPK2 by the Lm-sensing intracellular pattern-recognition receptor NOD2 is essential for the downstream stimulation of the NF-κB and MAPK pathways, NOD2-induced immune responses in macrophages and the control of listeriosis in vivo." (PMID 26834734, 2015).
lung squamous cell carcinoma (1 paper, 2021). "Meanwhile, RIPK2 expression was significantly lower in LUSC (lung squamous cell carcinoma) compared to that in the normal tissues." (PMID 33633788, 2021).
mouth ulcers (1 paper, 2023). "The proteins encoded by eight genes (PMEL, ARFIP1, FAM213A, GLUL, CADM2, FAIM3, RIPK2, and DECR1) have only one SNP instrumental variable and have a association with mouth ulcers using the Wald ratio method." (PMID 37369724, 2023).
oral squamous cell carcinoma (1 paper, 2022). "In oral squamous cell carcinoma, the abnormal expression of RIPK2 can impair human immunity and interfere with cell dedifferentiation, apoptosis and proliferation, thus promoting carcinogenesis of the oral mucosa." (PMID 35473583, 2022). "However, with the development of oral squamous cell carcinoma, the expression level of RIPK2 gradually declines." (PMID 35473583, 2022).
pancreatic ductal adenocarcinoma (1 paper, 2020). An infiltrating adenocarcinoma that arises from the epithelial cells of the pancreas. "After comprehensive analysis, we found that both MET and RIPK2 are related to the prognosis of pancreatic ductal adenocarcinoma and provided some associated clues for clinical application and basic experiment research." (PMID 33204717, 2020). "Besides, we predicted that both MET and RIPK2 promote autophagy in pancreatic ductal adenocarcinoma by gene set enrichment analysis." (PMID 33204717, 2020).
parasitic infections (1 paper, 2024). "In mammals, NOD1/NOD2 interacts with RIPK2, leading to the production of proinflammatory cytokines, to play roles in autophagy and anti-bacterial, -viral and -parasitic infections." (PMID 38715616, 2024).
peritonitis (1 paper, 2023). Inflammation of the peritoneum (tissue that lines the abdominal wall and covers most of the organs in the abdomen). "Early RIPK2-specific compounds (OD 36 and OD38) screened by this technique have shown ideal inhibitory activity against RIPK2 both in vitro and in vivo using an MDP-induced peritonitis mice model." (PMID 37324457, 2023).
rectal tumor (1 paper, 2023). "RIPK2 was found to be significantly upregulated in rectal tumor tissues compared with normal adjacent mucosa, suggesting that RIPK2 plays a vital role in the progression of IBD to CRC." (PMID 37324457, 2023).
Salmonella Infections (1 paper, 2013). Infections with bacteria of the genus SALMONELLA. "Thus iSCs require RIPK2/p38MAPK signaling in order to facilitate transcriptional responses to Salmonella infection." (PMID 24137162, 2013).
serous ovarian cancer (1 paper, 2022). "Overall, our study suggested that RIPK2 could act as a biomarker for Taxol treatment sensitivity in serous ovarian cancer and provides new insights into the mechanisms underlying Taxol resistance in serous ovarian cancer." (PMID 35477477, 2022). "In summary, we found that high expression of RIPK2 might be associated with the resistance of Taxol in serous ovarian cancer by identifying common DEGs and performing survival analysis with multiple datasets." (PMID 35477477, 2022). "Our studies suggested that high expression of RIPK2 is related to Taxol resistance in serous ovarian cancer, and that RIPK2 induces Taxol resistance through NOD1/RIPK2/NF-κB inflammatory pathway activation and tumor microenvironment changes." (PMID 35477477, 2022). "To assess the roles of RIPK2 in Taxol resistance in serous ovarian cancer, we identified its coexpressed genes in samples from patients treated with Taxol from the TCGA-OV dataset." (PMID 35477477, 2022). "In all three datasets, the RIPK2 high expression group and RIPK2 low expression group showed significant differences in survival in terms of OS and PFI, suggesting that high expression of RIPK2 is a risk factor for survival in patients with serous ovarian cancer." (PMID 35477477, 2022). "Thus, that higher expression of RIPK2 may lead to Taxol resistance in serous ovarian cancer was validated via combined DEG analysis and survival analysis." (PMID 35477477, 2022).
skin cutaneous melanoma (1 paper, 2022). "RIPK2 aggravated cytotoxic T lymphocyte (CTL) dysfunction and related to the poor efficacy of immune checkpoint blockade in skin cutaneous melanoma (SKCM) and kidney renal clear cell carcinoma (KIRC)." (PMID 35508972, 2022).
uterine carcinosarcoma (1 paper, 2023). A usually aggressive malignant neoplasm arising from the uterine corpus and less often the cervix. "Another study about pan-cancer analysis of the carcinogenic role of RIPK2 also illustrated that the gene amplification rate of RIPK2 in BRCA and uterine carcinosarcoma (UCS) was approximately 8.5%." (PMID 37324457, 2023).
cancer (55 papers, 2013 to 2026). A tumor composed of atypical neoplastic, often pleomorphic cells that invade other tissues. "Clinical studies have found that RIPK2 is associated with poor prognosis in pancreatic, lung, renal, and colorectal cancers and can be used as a prognostic marker." (PMID 41563982, 2026). "Beyond its role in inflammatory bowel disease and cancer, RIPK2 has also been implicated in a range of other pathological conditions." (PMID 40406369, 2025). "As classical pathways downstream of RIPK2, NF-κB signaling and the well-known cancer associated MAPK signaling were evaluated to investigate the specific mechanisms responsible for the RIPK2 induced malignant phenotypes in PC." (PMID 37016317, 2023). "Survival analysis showed that high expression of RIPK2 associated with poor prognosis in numerous cancers." (PMID 35508972, 2022). "As a remarkable association between the expression level of the RIPK2 gene and oncogenesis has been established, it has been shown as a potential target for cancer therapeutic intervention." (PMID 33790054, 2021). "RIPK2 is associated with drug resistance in malignant tumors." (PMID 41563982, 2026). "Second, the role of RIPK2 in different cancers is heterogeneous, and the causes of heterogeneity still have to be explored in depth, which can help with accurate and personalized treatment of cancer." (PMID 35508972, 2022). "Furthermore, RIPK2 mRNA abundance is strongly associated with RIPK2 protein abundance in various human cancer cell lines (r = 0.66, p = 2.2E–16)." (PMID 35115556, 2022). "In addition, we also found that RIPK2 was positively associated with cancer-associated fibroblasts (CAFs) in COAD, KIRP, and LUSC, but negatively associated with BRCA." (PMID 35473583, 2022). "However, RIPK2 inhibitors are promising therapeutic drugs for cancer, especially inflammation-associated cancer." (PMID 34356990, 2021). "In addition to PC, RIPK2 is frequently amplified and/or overexpressed in several other cancer types, and its mRNA overexpression is associated with significantly shorter overall survival in nine cancer types." (PMID 35115556, 2022). "Thus, RIPK2 overexpression is associated with poor prognosis in PC and many other cancers." (PMID 35115556, 2022). "Pan-cancer analyses revealed that RIPK2 exacerbates cytotoxic T-lymphocyte dysfunction and promotes resistance to immunotherapies through the JAK/STAT3 signaling pathway and γ-interferon response." (PMID 41563982, 2026). "Recent studies have shown that RIPK2 also plays pivotal roles in tumorigenesis and malignant tumor progression." (PMID 41563982, 2026). "Collectively, these findings suggest that RIPK2 is a versatile regulator of multiple signaling pathways, influencing diverse pathological processes from immune responses to cancer progression and cardiovascular diseases." (PMID 40406369, 2025). "Taken together, the observations reported in Section 2.1 suggest that NOD2/RIPK2 can impinge on metabolic pathways and can be regulated by tumor suppressor genes, linking inflammation, cancer and metabolism." (PMID 40095546, 2025). "The impact of immune and stromal cells within the tumor microenvironment on patient survival has been demonstrated, thereby providing evidence for the prognostic significance of RIPK2 across various cancer types." (PMID 38164277, 2024). "Compared with healthy tissues, cancerous tissues have higher RIPK2 levels, which are correlated with the prognosis of several types of cancer." (PMID 39309860, 2024). "RIPK2 plays a crucial role in intracellular signal transduction pathways, encompassing inflammation, autophagy, programmed cell death, and cancer." (PMID 38164277, 2024). "From this, we can find firm evidence for RIPK2 inhibition in the treatment of inflammation-related cancers, i.e., CRC." (PMID 37324457, 2023).
cancer (continued). "The online GEPIA tool analysis TCGA database indicates that the expressions of Groα, NOD1, NOD2 and RIPK2 in the cancer sample (n=519) are higher than those of in the normal tissue (n=44)." (PMID 37151389, 2023). "As the noteworthy association between RIPK2 expression level and tumorigenesis has been established, RIPK2 should be regarded as a potential target for cancer therapeutic intervention." (PMID 37324457, 2023). "XIAP also induces proinflammatory signaling by involving receptor-interacting serine/threonine kinase 2 (RIPK2) and production of interleukin 8 (IL-8) which leads to neutrophil recruitment in cancer and during infection." (PMID 36472768, 2023). "Last, is the attempt of coupling RIPK2 inhibitors with immune checkpoint inhibitors (ICIs) in cancer treatment." (PMID 37324457, 2023). "Despite limited evidence, pan-cancer analyses highlighted the role of RIPK2 in mediating malignant progression and immunotherapy resistance in multiple tumors." (PMID 37016317, 2023). "Unlike NOD1/2 inhibitors, targeting the downstream protein of NOD1/2 signaling pathway, RIPK2, to fight against cancer is more advantageous for the following three reasons." (PMID 37324457, 2023). "The result of pan-cancer analysis showed that RIPK2 was overexpressed in tumor tissues and served as a promising prognostic marker in multiple cancers." (PMID 35508972, 2022). "In this study, we investigated the expression, gene alteration landscape and prognostic value of RIPK2 in 33 cancers through various databases including Ualcan, cBioportal and Gene Expression Profiling Interactive Analysis 2 (GEPIA2)." (PMID 35508972, 2022). "We obtained the expression difference of RIPK2 in various cancer types in the TCGA database through the TIMER2.0 website." (PMID 35473583, 2022). "Overall, our research demonstrated the crucial role of RIPK2 in anti-tumor immune and immunotherapy response, providing new targets for cancer treatment." (PMID 35508972, 2022). "Compared with normal tissue, tumor tissue had a higher expression level of RIPK2 in various cancers." (PMID 35508972, 2022). "Recent studies have shown that RIPK2 was involved in the occurrence, development, and prognosis of cancer." (PMID 35508972, 2022). "For example, gefitinib, an EGFR inhibitor suppressing tumor growth and angiogenesis, was recently shown to inhibit the crosstalk between macrophages and cancer cells by blocking receptor interacting protein kinase 2 (RIPK2)." (PMID 35140725, 2022). "Nevertheless, there are no studies about the molecular mechanism by which RIPK2 alteration affect prognosis of human cancers, and our result provided a basis for further in-depth study of the carcinogenic effects of RIPK2." (PMID 35508972, 2022). "The single sample gene set enrichment analysis (ssGSEA) was used to explore immune infiltration, and genomic alterations of RIPK2 were also analyzed via cBio Cancer Genomics Portal (cBioProtal)." (PMID 35477477, 2022). "Subsequently, we analysed the expression of RIPK2 in various pathological stages of cancer tissues, and found that the expression of RIPK2 in most pathological stages of cancer tissues was higher than that in normal tissues." (PMID 35473583, 2022). "Taken together, the findings suggest that RIPK2 is a potent activator of c-Myc in PC and potentially in other cancers." (PMID 35115556, 2022). "In conclusion, this is the first study to propose a relationship between RIPK2 and CD8+ T cells, Tregs and cancer-related fibroblasts in malignant tumours, indicating that RIPK2 and immune cells are jointly involved in the formation and development of cancer." (PMID 35473583, 2022). "In order to explore the predictive value of RIPK2 in human cancer, GEPIA2 online tool was used to compare the prognostic difference between RIPK2 high expression group and low expression group." (PMID 35508972, 2022).